ALB (albumin)
Diseases named in the same sentence as ALB in open-access papers (continued):
Sharing a sentence is not in itself a finding about the gene and the disease.
melanoma (continued). "Systemically delivered albumin-NPs, loaded with pyropheophorbide-a, accumulate in melanoma lung metastases when a monoclonal antibody specific for gp75 antigen of melanoma (anti-gp75 mAb TA99) is injected in the melanoma-bearing animals." (PMID 32630815, 2020). "Despite a significant homology to the mammalian serum albumins, monoclonal antibodies produced by eight different rat hybridoma cell lines against the melanoma-specific B700 antigen cross-react only with murine albumin." (PMID 23476722, 2013). "The fact that both murine and human melanoma cells produce B700 antigen which is recognized by murine albumin antibodies suggests the presence of a murine-type albumin in human melanoma." (PMID 23476722, 2013). "The mechanisms governing the uptake of macromolecular therapeutic agents in human melanoma xenografts are currently being investigated in our laboratory, using albumin as a model molecule for macromolecular therapeutic agents." (PMID 12610516, 2003). "We have reported previously that our melanoma lines show an intertumour heterogeneity in the uptake of albumin that is governed primarily by intertumour differences in extracellular volume fraction." (PMID 12610516, 2003). "Further investigation using alternative outcome measures should be done in a larger cohort of melanoma patients to determine if the Fearon consensus criteria, WLGS, NLR, albumin and PNI may actually associate with physical function and morbidity." (PMID 39817619, 2025). "The increased clustering with BSA indicates that albumin may be able to bind hydrophobic molecules produced by S. aureus to enhance melanoma clustering." (PMID 39284707, 2024). "These multifaceted functions of albumin underscore its importance as a predictive biomarker in our model and suggest potential avenues for therapeutic interventions aimed at optimizing treatment outcomes in melanoma patients." (PMID 39600700, 2024). "The most accurate reason for this observation might be the extensive hemorrhage of melanoma that might falsify the results by washing out the albumin." (PMID 39324003, 2024). "The results showed that the growth of the B16F10 melanoma was suppressed in heterotopic B16F10 melanoma-bearing mice that had been treated with chlorambucil-loaded albumin nanoparticle-encapsulated liposomes compared to that of chlorambucil-loaded albumin nanoparticles." (PMID 33810483, 2021). "The drug delivery capacity of albumin-encapsulated liposomes against melanoma was also examined." (PMID 33810483, 2021). "Eleven genes were significantly differentially expressed between metastases and primary tumors, and ALB, ORM2, CRABP1, and APOH may be associated with the metastasis of melanoma." (PMID 34154655, 2021). "In addition, ADH‐1 treatment in a rat melanoma xenograft model increased tumor delivery of molecules with high binding affinity for plasma proteins (eg, ~70 kDa albumin), including Evans blue dye and the chemotherapeutic agent melphalan." (PMID 32617520, 2020). "Albumin-stabilized paclitaxel nanocrystals showed enhanced uptake by SPARC+ B16F10 melanoma cells and in vivo anti-tumor efficacy, and albumin-stabilized hydroxycamptothecin nanocrystals showed enhanced intratumor accumulation and prolonged survival time in MCF-7 model tumor-bearing mice." (PMID 30621141, 2019). "HCMel12 mouse melanoma cells were injected in mice and, upon macroscopic detection; tumour growth was monitored and daily injection of either a control protein (mouse serum albumin), Net4 or its laminin-binding mutant was administered." (PMID 27901020, 2016). "Events activating PI3K in mutated NRAS and BRAF-driven melanomas (i.e. PTEN loss), further expand the requirement of RAB7 and the roles of macropinocytosis (e.g. scavenging nutrients such as albumin and amino acids, lipids and extracellular ATP) to a broader spectrum of melanocytic lesions." (PMID 26008978, 2015).
melanoma (continued). "Intratumour heterogeneity in the uptake of blood-borne technetium-labelled human serum albumin (99mTc-HSA) was studied in human melanoma xenografts in an attempt to identify transport barriers leading to inadequate and heterogeneous uptake of macromolecular therapeutic agents in tumours." (PMID 12610516, 2003). "Notably, previous studies have demonstrated the ability of the N‐cadherin antagonist peptide ADH‐1 to increase EC monolayer permeability in vitro, and rapidly enhance tumor blood vessel permeability to albumin‐bound Evans blue dye in pre‐clinical models of melanoma." (PMID 32617520, 2020). "Some cancers, e.g., breast, melanoma, head, and neck, overexpress SPARC receptors that facilitate the cellular uptake of particle–albumin complexes." (PMID 40284485, 2025). "In melanoma, the Fearon consensus criteria, WLGS, NLR, albumin and PNI all predicted worse overall survival." (PMID 39817619, 2025). "Many cancer types including breast, esophageal, head and neck, melanoma, ovarian, and SCLC showed significantly positive effects of high serum albumin on OS primarily in the cohort with ICB treatment." (PMID 35393553, 2022). "Another group reported, in an in vitro assay, that paclitaxel-loaded albumin nanoparticle-encapsulated liposomes inhibited the proliferation and migration of B16F10 melanoma cells more strongly than paclitaxel-loaded albumin nanoparticles." (PMID 33810483, 2021). "Hybrid PDA NPs containing only human serum albumin (HSA) or bovine serum albumin (BSA) and transferrin were synthesised and exposed to human fibroblasts, mouse melanoma, and mouse macrophages." (PMID 32272786, 2020). "Several lines of study to improve the efficacy of PTX and reduce the toxicity of PTX have been performed such as nanoparticle formulation albumin-bound PTX (nab-PTX) in metastatic breast cancer and melanoma." (PMID 29486738, 2018). "Regarding serum albumin (ALB), our data confirm its robust prognostic role in melanoma immunotherapy response: levels remained consistently higher in the clinical benefit group across all time points, with T1 ALB ≥ 41.3 g/L independently associated with favorable treatment outcomes." (PMID 41561757, 2025). "Interestingly, although GBM presented with higher pericyte coverage, the amount of albumin positive vessels was higher, indicating higher vessel leakage in GBM than melanoma." (PMID 39324003, 2024). "A subsequent study of 373 melanoma patients evaluating the combination of S100B, MIA, LDH, and albumin as biomarkers reported that S100B had the greatest sensitivity for detecting new metastases compared to MIA, LDH, or albumin." (PMID 22220281, 2011). "GRIm’s reliance solely on laboratory parameters (NLR, LDH, and albumin) without including clinical factors such as performance status or metastatic burden may explain its limited prognostic performance in melanoma." (PMID 41010656, 2025). "To directly test whether albumin differentially affects KIs including dabrafenib and encorafenib, we treated A375 melanoma cells with a KI dose response for 2 hours in the presence or absence of physiologic levels of HSA and measured downstream p-ERK1/2 levels by immunofluorescence." (PMID 35486732, 2022). "On the 40th day (6th week) post treatment, sera levels of albumin (g/dL), calcitonin (ρg/ml), CEA (ng/ml), CRP (mg/ml), or LDH (U/L) in melanoma mice were not significantly different between treatment groups and control groups (data not shown)." (PMID 30611221, 2019). "In particular, TAT peptide-coated Ag NPs were used to inhibit B16 melanoma growth; PVP-stabilized Ag NPs were developed for triple-negative breast cancer treatment; and mouse serum albumin-coated Ag NPs were designed for the reduction of murine fibrosarcoma growth." (PMID 35631598, 2022). "There is no relevant functional study on the relationship between ALB, ORM2, CRABP1, and APOH and melanoma metastasis, which may represent future candidates." (PMID 34154655, 2021).
melanoma (continued). "Abraxane (Celgene), an albumin-particle bound paclitaxel, FDA-approved for advanced non-small cell lung cancer, metastatic breast cancer, and metastatic pancreatic cancer, is actually under investigation also in melanoma patients." (PMID 32630815, 2020).
neutropenia (54 papers, 2013 to 2026). A decrease in the number of neutrophils found in the blood. "The study identified neutropenia, male gender, elevated serum creatinine, and low albumin levels as significant risk factors for 30-day all-cause mortality." (PMID 39963642, 2025). "Univariate analysis identified BMI classification (P=0.010), ECOG score (P=0.001), and baseline albumin (ALB) stratification (P = 0.001) as potential factors associated with the development of severe neutropenia (grade 3-4)." (PMID 40620712, 2025). "Baseline BMI classification, baseline white blood cell (WBC) count and baseline albumin (ALB) stratification were factors associated with protection against grade 3-4 neutropenia." (PMID 40620712, 2025). "Female, total gastrectomy, and lower albumin concentration were significantly associated with neutropenia." (PMID 27863481, 2016). "Serum albumin levels and folic acid supplementation were significantly associated with the severity of pancytopenia and neutropenia." (PMID 27128679, 2016). "The enhanced efficacy and reduced toxicity with respect to neutropenia may be associated with the more effective intracellular delivery of paclitaxel through the albumin-based nanoparticle technology." (PMID 28883517, 2017). "Zelenetz identified older age, low albumin, presence of hepatic dysfunction, bone marrow involvement by the disease and/or low neutrophil at diagnosis as predicting factors for high risk of neutropenia in the first cycle of chemotherapy and thereby potential risk for lower dose intensity." (PMID 25909361, 2015). "Nanoparticle albumin-bound (nab)-paclitaxel is a biologically interactive, albumin-bound formation of paclitaxel particle developed to avoid or minimize the toxicities associated with traditional paclitaxel and docetaxel such as sensory neuropathy, neutropenia and severe hypersensitivity." (PMID 34727875, 2021). "Besides different treatment regimens, several factors such as older age, advanced stage, impaired kidney function, impaired patients' performance status, decreased pretreatment absolute neutrophil counts and serum albumin level were reported to be associated with severe neutropenia or FN." (PMID 32426291, 2020). "Nevertheless, and as high serum albumin may be associated with enhanced risk of developing neutropenia in this type of patients treated with Gem/NabP, close monitoring of adverse events and tolerability is recommended in order to adjust the dosage and treatment schedules." (PMID 33008332, 2020). "Our analysis revealed that grade ≥3 neutropenia was significantly associated with the ECOG score (P = 0.008), baseline serum ALB level (P = 0.031), baseline WBC count (P = 0.007), and BMI classification (P = 0.035)." (PMID 40620712, 2025). "Compared with patients with a baseline ALB level <4.0 g/dL, patients with a baseline ALB level >4.0 g/dL had a lower incidence of neutropenia." (PMID 40620712, 2025). "Our results showed that an incremental albumin level was protective against the occurrence of leukopenia and neutropenia after HIPEC." (PMID 36814253, 2023). "Risk factors of DOC-induced neutropenia are reportedly advanced aging, leucopenia, neutropenia, serum creatinine elevation, and serum albumin decrease at baseline, and a history of localized radiation therapy." (PMID 37945672, 2023). "The highest incidence of TRAEs were decreased serum albumin (46.5%), increased bilirubin (29.5%), transaminase (27.1%), and neutropenia (22.5%)." (PMID 37392168, 2023). "Several covariates were explored to assess their impact on G4 neutropenia: dose, neutrophils at baseline, albumin, AAG, and BSA." (PMID 34739582, 2022). "The biosafety and efficacy of injecting GSF fusion protein and recombinant human serum albumin were studied for preventing chemotherapy-induced neutropenia." (PMID 34899721, 2021).
neutropenia (continued). "However, standard paclitaxel has considerable toxicity compared with the nanoparticle albumin-bound (nab) colloidal formulation, nab-paclitaxel (nabP), which is associated with a lower incidence of vehicle-related hypersensitivity reactions, neurotoxicity, and neutropenia." (PMID 31516389, 2019). "In the present study, serum albumin levels were identified as the significant factor that affected the severity of pancytopenia and neutropenia." (PMID 27128679, 2016). "The level of albumin in BAL fluid was increased in mice challenged with LPS during neutropenia recovery compared with control mice, whereas treatment with imatinib or nilotinib prior to LPS significantly attenuated the albumin level." (PMID 23787115, 2013). "Univariate analyses identified that lactate, albumin, SOFA score, APACHE, renal replacement therapy, septic shock, neutropenia, SEER summary stage, underlying diagnosis, SACT, underlying cancer and surgery were significantly different in day-90 non-survivors compared to survivors." (PMID 39871712, 2025). "Therefore, baseline ALB level was included in this study to explore the relationship with neutropenia." (PMID 40620712, 2025). "In addition, gender, leucovorin use, and various serum biomarkers such as albumin, hemoglobin, monocytes, and lactate dehydrogenase have been reported as predictors of chemotherapy-induced neutropenia or febrile neutropenia in other cancer types." (PMID 39570570, 2024). "An incremental albumin level was protective against the occurrence of leukopenia and neutropenia." (PMID 36814253, 2023). "Their occurrence is favored by prolonged neutropenia, older patient age, and low albumin levels." (PMID 36076988, 2022). "Neutropenia was a common adverse reaction of paclitaxel albumin nanoparticles." (PMID 34109887, 2021). "The control and intervention groups were similar in sex distribution, underlying hematological disease, history of fungal infections, presence of central catheter, granulocyte colony-stimulating factor usage, minimum albumin levels, and severity of neutropenia." (PMID 26376622, 2016). "Serum albumin levels and folic acid supplementation are the important factors affecting the severity of MTX-related pancytopenia and neutropenia." (PMID 27128679, 2016). "Immunonutritional indices, including the Hemoglobin-Albumin-Lymphocyte-Platelet (HALP) score, the Prognostic Nutritional Index (PNI), and the C-reactive protein/albumin ratio (CAR), as well as the Clinical Index of Stable Febrile Neutropenia (CISNE) score were calculated." (PMID 41590334, 2025). "Days of illness at IVIG initiation were longer, serum albumin was higher and total bilirubin was lower in patients with neutropenia, although these variables were not statistically significant." (PMID 34150684, 2021). "Albumin-bound NPs translated PTX into the commercial cancer drug Abraxane, for which the phase III data indicated that albumin allowed a 1.5-fold increase in MTD of Abraxane than that of free PTX; however, when the dose was beyond MTD, 25% of patients notably suffered from neutropenia." (PMID 34603454, 2021). "Besides, serum albumin level was correlated to ≥grade 3 neutropenia event in univariate analysis while this correlation is not significant in multivariate analysis (p = 0.055)." (PMID 32426291, 2020). "A large-scale, multicenter clinical study found that risk factors of IFD among chemotherapy patients with malignant hematologic disease included neutropenia, AML or MDS, non-CR patients who receipt of induction chemotherapy or repeat induction chemotherapy, decreased serum albumin levels, and CVC." (PMID 37520379, 2023).
hypothyroidism (53 papers, 2008 to 2025). Abnormally low levels of thyroid hormone. "Hypothyroidism causes increased vascular permeability via vascular endothelial growth factor, albumin extravasation, and inadequate lymphatic drainage, leading to effusion leakage into the body cavities." (PMID 40242698, 2025). "Data collected on the various independent variables was analyzed by the Bayesian logistics regression method and the only factor that was found to be associated with hypothyroidism was reduced serum albumin ≤ 2.5 g/dl." (PMID 38373933, 2024). "Hypothyroidism causes increased permeability of albumin in the pericardial capillaries, which causes a decrease in the colloid osmotic pressure gradient between the pericardium and pericardial space, resulting in fluid accumulating in the pericardial space." (PMID 38803753, 2024). "Only low serum albumin was found to be strongly associated with hypothyroidism; Bayesian OR 132.57 (CI 9.13–567.10) with a frequentist OR of 37 and a p value of 0.001." (PMID 38373933, 2024). "Both approaches yielded similar findings hence strengthening the evidence supporting the association between low albumin levels and the risk of hypothyroidism." (PMID 38373933, 2024). "The top five hub genes associated with hypothyroidism are ALB, MAPK1, SPP1, PPARG, and MIF, whereas those associated with hyperthyroidism are ALB, FCGR2B, CD44, LCN2, and CD74." (PMID 32500465, 2020). "Other proposed mechanisms are associated hypothyroidism and decreased albumin and protein levels caused by starvation." (PMID 31123651, 2019). "Therefore, children and adolescents that have severely low levels of serum albumin should be screened for hypothyroidism and linked to endocrinologists for care." (PMID 37398057, 2023). "Typically pericardium is impermeable to proteins, whereas, in hypothyroidism, there is a rise in pericardial permeability and reduced lymphatic drainage of the albumin that causes leakage of proteins into the pericardial space, leading to accumulation of fluid in the pericardial space." (PMID 34786222, 2021). "SCr, BUN, UA, TP, ALB, and autoantibody levels are modifiable factors that can be improved through early treatment to improve renal function and strengthen nutrition support, in order to reduce risk among LN patients with hypothyroidism." (PMID 32357838, 2020). "Additional grade 3-4 AEs included hypothyroidism (7.5%), decreased albumin (7.5%), and several events occurring at 5.0% (skin pruritus, diarrhea, and proteinuria)." (PMID 40821815, 2025). "The extravascular accumulation of albumin is reportedly evident after only two to three months of hypothyroidism." (PMID 40242698, 2025). "Pericardial effusion is another known complication of hypothyroidism that occurs as an increased permeability of epicardial vessels and decreased lymphatic drainage of albumin." (PMID 38933628, 2024). "The effects of hypothyroidism on factor X and protein S activities were still prominent after adjustment for serum albumin as an indicator of NS severity." (PMID 39323731, 2024). "TBG and albumin are important carriers of thyroid hormones and act as buffers of serum levels of thyroxine before hypothyroidism eventually occurs." (PMID 38373933, 2024). "This study found that patients with a reduced serum albumin were more likely to have hypothyroidism compared to those that had normal levels of the same." (PMID 38373933, 2024). "Serum albumin also acts as a buffer of serum levels of thyroxine before hypothyroidism eventually occurs and once it is lost in urine together with thyroglobulin, the serum concentration of the thyroid hormones also decreases." (PMID 38373933, 2024). "Patients with higher UP had higher levels of TSH, s-Cr, total cholesterol; had lower levels of FT4, FT3, eGFRcre, 24hcCcr, albumin, hemoglobin, and HbA1c; had higher prevalence of subclinical and overt hypothyroidism; and took more THRT and ACE-I/ARB." (PMID 36056164, 2022).